TSLP (thymic stromal lymphopoietin)
Diseases named in the same sentence as TSLP in open-access papers (continued):
Sharing a sentence is not in itself a finding about the gene and the disease.
lung disease (11 papers, 2012 to 2023). "Within this genomic region, there is a compelling candidate gene with experimental evidence of female-specific effects on lung disease, thymic stromal lymphopoietin (TSLP)." (PMID 22272212, 2012). "Third, considering the redundant nature of cytokines, future studies should focus on whether combined targeting of IL‐25/IL‐33/TSLP is necessary to completely block the progressive fibrotic lung diseases." (PMID 36082495, 2022). "Therefore, the interaction between IL-4 and TSLP could contribute to the development of these lung disorders." (PMID 34440780, 2021). "Compared with traditional biomarkers such as IL-5, TSLP, and TARC, microbiota biomarkers also represent a vital role in the development and progress of lung diseases." (PMID 34621687, 2021). "Receiver operating characteristic curves of the TSLP and IL-33 levels revealed clear differences between the IPF and NC groups (AUC = 0.655 and 0.706, respectively), as well as between the IPF and the other lung disease groups (AUC = 0.786 and 0.781, respectively)." (PMID 28202030, 2017).
parasitic infections (11 papers, 2017 to 2025). "Alarmin cytokines including IL-25, IL-33, and thymic stromal lymphopoietin (TSLP) function as danger signals to trigger host immunity in response to tissue injury caused by pathogenic factors such as parasitic infections." (PMID 39559705, 2024). "TSLP has been shown to regulate inflammation in the colon by inducing a Th2 response to fight parasite infection." (PMID 37427591, 2023). "In the colon, TSLP induction leads to a productive Th2 response that eliminates parasite infection and mediates mucosal healing after exposure to an inflammatory insult." (PMID 37427591, 2023). "It has been shown that the TSLP-mediated skewing of the T cell response toward a Th2 phenotype and/or suppression of exacerbated Th1 responses can be protective in certain parasitic infections and colitis models." (PMID 32103153, 2020). "Upon parasitic infection, damaged intestinal epithelial cells release soluble factors known as alarmins, such as thymic stromal lymphopoietin (TSLP), IL-25, and IL-33." (PMID 33371444, 2020). "The function of tuft cells was rather unclear until three studies recently demonstrated that tuft cells initiated type II immune response by secreting the cytokine IL25, IL33, and TSLP (thymic stromal lymphopoietin) following parasite infections in the murine intestine." (PMID 29163195, 2017). "Overall, the data available in the literature seem to suggest that the pro-homeostatic effects of TSLP might be tissue specific (mainly in the gastrointestinal tract) and context specific (parasitic infections and colitis), and manifest within a narrow window of concentrations." (PMID 32103153, 2020). "ILC2 cells are activated by IL-33, IL-25, and thymic stromal lymphopoietin (TSLP), leading to the production of cytokines such as IL-4, IL-5, and IL-13, which are involved in allergic responses and defense against parasitic infections." (PMID 39876010, 2025).
colitis (10 papers, 2015 to 2025). Inflammation of the colon. "Collectively, these findings demonstrate for the first time that an anti-TSLP antibody is effective in a mouse model of colitis-associated CRC." (PMID 40873585, 2025). "Our results suggest that blocking TSLP signaling may be necessary to predispose the mouse colon to ICB-induced colitis." (PMID 37427591, 2023). "Interestingly, loss of TSLP signaling in immunocompetent mice treated with ICB therapy leads to colitis, which is a common immune adverse event observed in cancer patients treated with ICB." (PMID 37427591, 2023). "TSLP signaling in circulating cells prevents CD4+ T cell–induced lethal colitis in Rag1KOTslprKO mice." (PMID 37427591, 2023). "This is consistent with previous studies demonstrating the reduction in inflammatory Th1 cell response after TSLP induction, which prevents colitis." (PMID 37427591, 2023). "Three main studies have shown an important role of TSLP in DSS-induced colitis using two knock-out mouse models, where TSLP or the TSLP receptor (TSLPR) gene was deleted." (PMID 26546058, 2015). "Oral administration of LL-TSLP significantly decreased the DAI at D4, showing that TSLP-secreted L. lactis delayed clinical signs of colitis, especially feces softening and bleeding." (PMID 26546058, 2015). "In order to understand the effect of TSLP on the early phase of colitis we analyzed the Treg proportion in MLN at day 4 and day 12 of colitis." (PMID 26546058, 2015). "The third study has also demonstrated a protective role of TSLP during DSS-induced colitis followed by a recovery phase." (PMID 26546058, 2015). "TSLP signalling on DCs promotes Tregs in the gut to prevent bacteria‐mediated inflammation and TSLP signalling via interaction between DCs and T cells promotes Treg development, resulting in protection against colitis in a mouse model." (PMID 39654685, 2024). "TSLP signaling prevents lethal colitis during homeostatic CD4+ T cell expansion." (PMID 37427591, 2023). "TSLP signaling contributes to resistance to ICB-induced colitis in mice." (PMID 37427591, 2023). "TSLP showed an anti-inflammatory protective role in DSS-induced colitis." (PMID 26546058, 2015). "However despite its key role in allergic response, TSLP has been shown to have protecting effects in a mouse model of colitis." (PMID 26546058, 2015). "Although there are differences in the hypotheses and explanations, all these data show an important role of TSLP in the protection of epithelial integrity and colitis reduction." (PMID 26546058, 2015). "Therefore we conclude that, short and early TSLP treatment allowed a better protection against colitis than a longer treatment as demonstrated by a lower severity as well as a delay in the disease." (PMID 26546058, 2015). "Thymic stromal lymphopoietin showed an anti-inflammatory protective role in DSS-induced colitis." (PMID 26546058, 2015). "Together, these results identify TSLP as a major regulator of homeostatic CD4+ T cell expansion in the adult colon, thereby preventing lethal colitis." (PMID 37427591, 2023). "Recent reports suggest that cytokines known to activate ILC2s, such as IL-33 and thymic stromal lymphopoietin (TSLP), have protective effects against DSS-induced colitis." (PMID 36268010, 2022). "Our studies into the impact of baseline TSLP expression on homeostatic CD4+ T expansion in barrier sites have revealed that colonic TSLP signaling is essential for suppressing the overexpansion of T cells and lethal colitis in adult animals." (PMID 37427591, 2023). "To understand the role of TSLP in inflammation, we constructed Lactococcus lactis strain producing TSLP (LL-TSLP) and investigated the effect of its administration on dextran sulfate sodium (DSS)-induced colitis model in mice." (PMID 26546058, 2015). "Thus, novel therapeutics targeting TSLP in the colon may prove effective for the treatment and prevention of IBD and ICB-induced colitis." (PMID 37427591, 2023).
influenza (10 papers, 2020 to 2025). An acute viral infection of the respiratory tract, occurring in isolated cases, in epidemics, or in pandemics; it is caused by serologically different strains of viruses (influenzaviruses) designated A, B, and C, has a 3-day incubation period, and usually lasts for 3 to 10 days. "On the other hand, while the immune activity of IFN-λ2 plus vaccine is dampened in Tslpr-/- mice, antibodies in both serum and BAL fluids remain unaffected in TSLP-deficient mice administrated with IFN-αB/D-involved influenza vaccine." (PMID 37809098, 2023). "TSLP signaling is also required for virus-specific CD8+ T cell responses when a live-attenuated influenza vaccine is administered intranasally." (PMID 40035515, 2025). "Our previous studies showed that TSLP signaling enhances influenza vaccine-mediated Tfh and GC B cell responses following mucosal immunization and is required for IFN-λ-boosted Tfh and GC B cell responses (19, –, 22)." (PMID 40035515, 2025). "Our previous studies demonstrated that TSLP exhibits adjuvant activity on influenza subunit vaccines when immunized by rectal routes and improves the efficacy of rectally administered influenza vaccines." (PMID 40035515, 2025). "TSLP signaling is also required for interferon-λ-induced mucosal adaptive immunity after being intranasally immunized with influenza vaccines, highlighting its importance as a mucosal adjuvant." (PMID 40035515, 2025). "Our work further corroborates what previous studies have shown, that TSLP shapes effector T cell responses following influenza infection." (PMID 34997007, 2022). "Here we found that recombinant TSLP can greatly improve the efficacy of intranasal influenza vaccines." (PMID 34659250, 2021). "Here, we found that TSLP acts directly on CD8+ T cells to limit their responses in most tissues during primary influenza infection, with more virus-specific Crlf2-/- cells than virus-specific WT cells." (PMID 33439121, 2021). "There are conflicting reports of the role of TSLP on CD8+ T cells during primary influenza infection, and the effects of TSLP on memory CD8+ T cells and secondary responses to acute viral infections have not been characterized." (PMID 33439121, 2021). "Previous work showed that interferon-λ (IFN-λ) can trigger the synthesis of thymic stromal lymphopoietin (TSLP) by specialized epithelial cells in the upper airways of mice, thereby improving the performance of intranasally administered influenza vaccines." (PMID 34659250, 2021). "We demonstrated that TSLP can boost antibody production and T cell responses, and we showed that TSLP is the crucial factor that mediates the strong adjuvant activity of IFN-λ on mucosal influenza vaccines." (PMID 34659250, 2021). "To assess the role of TSLP on CD8+ T-cell responses during influenza infection, we adoptively transferred P14 T cells (TCR transgenic CD8+ T cells specific for LCMV glycoprotein 33, gp33) into WT mice." (PMID 33439121, 2021). "Taken together, these results demonstrated that TSLP enhances protective antiviral immunity induced by influenza subunit vaccines applied by the intranasal route." (PMID 34659250, 2021). "Similar immune-enhancing effects of IFN-λ and TSLP were observed if an influenza subunit vaccine was delivered to mice via the rectal route." (PMID 34659250, 2021). "Previous work revealed that IFN-λ can boost the efficacy of intranasal influenza subunit vaccines via an indirect mechanism that involves IFN-λ-mediated production of TSLP by specialized epithelial cells in the airways." (PMID 34659250, 2021). "In this study, we demonstrate that recombinant TSLP exhibited strong adjuvant activity on various intranasal influenza vaccines." (PMID 34659250, 2021). "Our previous studies have shown that mice intranasally or rectally immunized with TSLP and universal influenza vaccines can boost serum vaccine-specific systemic IgG1 and mucosal IgA levels and effectively resist influenza virus challenge in a TSLPR-dependent manner." (PMID 40035515, 2025).
influenza (continued). "Thus, the reported roles of TSLP in CD8+ T-cell responses during primary influenza infection have been somewhat variable, possibly at least in part due to variability in the experimental models/design/animal facilities." (PMID 33439121, 2021). "Interestingly, IFN-λ or TSLP alone also improved the performance of influenza vaccines applied by the rectal route." (PMID 34659250, 2021). "Interestingly, RNA-Seq data indicated that TSLP suppresses several genes that are related to cell cycle, apoptosis, or protection from virus in influenza infection, with an increased number of virus-specific Crlf2-/- CD8+ T cells." (PMID 33439121, 2021). "We next investigated whether the effects of TSLP on primary CD8+ T-cell responses that we observed with influenza (where infection is at a barrier surface where TSLP is expressed) might extend to a systemic infection such as acute LCMV infection." (PMID 33439121, 2021). "Although the IFN-λ/TSLP axis might be employed to improve the efficacy of existing influenza vaccines, current evidence that the TSLP system is of crucial importance for vaccine-induced protective immunity is quite limited." (PMID 34659250, 2021). "TSLP acts directly on CD8+ T cells during primary influenza infection." (PMID 33439121, 2021). "We previously showed that TSLP can boost influenza vaccine-induced serum IgG1 titers in mice, but it remained unclear whether enhanced antibody titers in TSLP-treated mice would provide better protection from influenza virus-induced disease." (PMID 34659250, 2021). "Here we demonstrate that protein-only influenza vaccines containing either IFN-λ or TSLP boosted antigen-specific IgG1 and IgA responses and enhanced the resistance of mice to influenza virus challenge, irrespective of whether the vaccines were applied via the intranasal or the rectal route." (PMID 34659250, 2021). "Thus, TSLP negatively regulated the secondary CD8+ T cell response to either an acute local lung infection (influenza) or an acute systemic infection (LCMV), revealing a previously unappreciated role for TSLP in directly modulating memory CD8+ T cell recall responses." (PMID 33439121, 2021). "Our previous findings showed that during intranasal influenza vaccine administration, IFN-λ elicited a germinal center reaction by inducing respiratory microfold cells to secrete TSLP and promoting DC migration to lymph nodes." (PMID 40035515, 2025). "TSLP interacts with TSLPR on CD11b+ DCs to participate in immune responses and promote the long-term antiviral immunity of CD8+ T cells following influenza infection in mucosal tissues, especially in the respiratory tract." (PMID 37809098, 2023). "The same results can be observed when TSLP is given together with another IAV vaccine haemagglutinin (HA), a commercial influenza vaccine containing particle-derived hemagglutinin." (PMID 37809098, 2023). "TSLP signaling was essential for the enhancing effect of IFN-λ on rectally administered influenza vaccines, illustrating the importance of the IFN-λ/TSLP axis for mucosal protective immunity in general." (PMID 34659250, 2021). "Influenza infection induced the release of IFN-λ, which triggered M cells to produce thymic stromal lymphopoietin (TSLP) in the upper airways." (PMID 33362795, 2020). "One study reported that TSLP does not affect the control of primary influenza infection or viral‐specific CD8+ T‐cell responses." (PMID 37165746, 2023). "Studies using adoptive co‐transfer models of wild‐type and Crlf2−/− TCR transgenic cells also differed related to the actions of TSLP on CD8+ T cells, with TSLP either enhancing primary CD8+ T‐cell responses or limiting their responses during primary influenza infection." (PMID 37165746, 2023). "One study using Crlf2-/- mice indicated that TSLP does not affect the control of influenza infection nor affect virus-specific CD8+ T cell responses during primary infection." (PMID 33439121, 2021).
influenza (continued). "Importantly, TSLP limited memory CD8+ T cell recall responses, with enhanced cellular responses in multiple tissues of Crlf2-/- T cells following either secondary influenza infection or LCMV systemic infection." (PMID 33439121, 2021). "Interestingly, IL-7-boosted Tfh and GC B cell reactions induce both influenza vaccine-specific IgG1 and IgG2c production, which conflicts with our finding that TSLP preferentially induces IgG1 rather than IgG2c responses." (PMID 40035515, 2025). "Interestingly, TSLP limited the primary CD8+ T-cell response to influenza but did not affect T cell function nor significantly alter the number of memory CD8+ T cells generated after influenza infection." (PMID 33439121, 2021). "Another report concluded that TSLP enhances CD8+ T-cell responses during primary influenza infection, but that this was not due to a direct action on CD8+ T cells and instead was an indirect effect on CD8+ T-cell responses resulting from TSLP-induced IL-15 production by dendritic cells." (PMID 33439121, 2021). "Whereas the stimulating effect of IFN-III as an adjuvant in influenza vaccine is canceled if administered intraperitoneally or subcutaneously, implying that these non-mucosal sites do not express significant IFN-III-responsive cells to produce TSLP-dependent antibodies." (PMID 37809098, 2023).
skin cancer (10 papers, 2016 to 2025). "Previous research has demonstrated that TSLP can have bidirectional effects in solid tumors, such as breast and skin cancers." (PMID 40787610, 2025). "While promoting neoplastic growth in breast and pancreatic tissues, TSLP exhibits a protective role against skin neoplasm carcinogenesis." (PMID 38539468, 2024). "Alternatively, TSLP actions have demonstrated a protective role in the carcinogenesis of skin neoplasms." (PMID 34306760, 2021). "On a molecular level, activation of T-cells by TSLP was shown to inhibit the growth of β-catenin-dependent skin tumors." (PMID 34306760, 2021). "Conversely, Di Piazza and Demehri demonstrated that TSLP exerted a tumor-suppressing role in the murine model of skin cancer." (PMID 32351590, 2020). "TSLP also exhibits contrasting effects on the progression of breast and skin cancers, although these effects have not been clearly linked to dosage." (PMID 40787610, 2025). "The efficacy of transient TSLP induction in delivering lasting tumor-specific immunity in the skin emphasizes the benefit of using topical TSLP inducers (e.g., calcipotriol) as safe and accessible modalities for skin cancer immunoprevention." (PMID 39744942, 2025). "In human studies TSLP expression was always associated with a pro-tumor function with the exception of colorectal cancer, whereas an anti-tumor function was found in those mouse models (i.e., pancreatic, breast, and skin cancers), in which high levels of systemic TSLP were reached." (PMID 33042121, 2020). "Notably, a tumor-suppressive effect of TSLP-TSLPR signaling recently has been demonstrated in mouse models of skin cancer by promoting a T cell-mediated antitumor response and inhibiting skin accumulation of immunosuppressive Gr-1+ myeloid cells." (PMID 26919238, 2016). "Infliximab could reduce skin inflammation in NS, decreasing the expression of TSLP, IL-6, and IL-8, but the treatment is not recommended considering the risk of skin cancers and recurrent infections reported in patients." (PMID 34041207, 2021). "TSLP directly signals CD4+ and CD8+ T-cells in the skin, inhibiting cancer development, particularly β-catenin-dependent skin tumors." (PMID 38539468, 2024). "To determine whether Th2 polarization was required in TSLP-activated CD4+ T cell immunity against skin carcinogenesis, we examined skin tumor development in Il4ra–/– (Il4rKO) and Tslptg Il4rKO mice." (PMID 39744942, 2025). "Without mature T and B cells, TSLP overexpression did not impact skin tumor development in Tslptg Rag1KO compared with Rag1KO and WT mice." (PMID 39744942, 2025). "Mice lacking IL-4Rα showed earlier skin tumor onset and higher tumor counts over time compared with mice with intact IL-4Rα, regardless of TSLP expression." (PMID 39744942, 2025). "They found that calcipotriol application to the skin induced TSLP expression and resulted in a delay in developing skin cancer compared to no treatment." (PMID 34306760, 2021).